MTOR (mechanistic target of rapamycin kinase)
Diseases named in the same sentence as MTOR in open-access papers (continued):
Sharing a sentence is not in itself a finding about the gene and the disease.
tumor (continued). "Furthermore, combined GLS and mTOR inhibition resulted in massive GBM cell death and tumor growth inhibition in a xenograft model, underscoring the importance of compensatory glutamine metabolism in promoting GBM resistance to mTOR inhibitor treatment." (PMID 32013066, 2020). "Compared with the NC group, the expression levels of p-PI3K, p-AKT, p-mTOR, and p-p70S6K in the tumor tissue in the si-SNHG1 group were significantly reduced; the expression levels of p-PI3K, p-AKT, p-mTOR, and p-p70S6K in the tumor tissue in the si-SNHG1+EZH2 group were significantly increased." (PMID 33194612, 2020). "Interestingly, FAK is closely related to relevant signaling pathways, including the mTOR signaling pathway, HIF-1 signaling pathway, and PI3K-Akt signaling pathway, which are synergistically involved in tumor migration, invasion, metastasis and recurrence." (PMID 33186122, 2020). "These TSC genes are tumor-suppressor genes and play the role as a GTPase-activating protein (GAP) toward Rheb, which is a major regulator of the mammalian target of rapamycin (mTOR)." (PMID 32887218, 2020). "Our results raise the possibility that tumour cells should not be the primary target of mTOR inhibition." (PMID 32567735, 2020). "Furthermore, in vitro and in vivo experiments showed that SLFN11 likely functions as a tumor suppressor in HCC progression and metastasis by targeting RPS4X via the mTOR signaling pathway." (PMID 32292519, 2020). "We analyzed tumor samples from 24 patients and using IHC studied expression of select molecular markers known to be involved in the pathogenesis of HPV+ HNSCC including ERCC1, 4EBP1, AMPK, AKT, S6, PI3K, mTOR, and PTEN." (PMID 32944296, 2020). "Checkpoint blockade antibodies against CTLA-4, PD-1, and PD-L1, can restore glucose in tumor microenvironment, permitting T cell glycolysis and IFN-γ production, and blocking PD-L1 directly on tumors dampens glycolysis by inhibiting mTOR activity and decreasing expression of glycolysis enzymes." (PMID 33489906, 2020). "Similarly, phosphorylation of RON has been shown to activate the PI3K-Akt-mTOR pathway in tumor cells, which further links MSP-RON to energy metabolism and inflammation since mTOR is a key regulator of energy metabolism and mediates immune suppression." (PMID 33117355, 2020). "Through rescue assays, we confirmed that IGF-1, the activator of PI3K/AKT/mTOR pathway, could counteract the suppressive influence of ZEB1-AS1 silence on tumor growth and development of TC." (PMID 32231464, 2020). "Image analysis of 18F-mFBG PET data showed correlation to tumour NET-1 protein expression, while further studies are needed to elucidate whether NET-1 upregulation induced by blocking mTOR might be a useful adjunct to 131I-mIBG therapy." (PMID 33262374, 2020). "In the analysis of relevant signaling pathway factors, in the transplanted tumor tissue of the sequential group, the expression levels of p‐AKT and p‐mTOR were significantly lower than those in the other groups and there was a significant difference from those in the other three groups." (PMID 32073228, 2020). "The mTOR signalling pathway was altered in subtype-1 tumours but not in subtype-2 tumours (combined score = 85, hypergeometric test; p = 2.1 × 10−19)." (PMID 31988390, 2020). "We conclude that increased mTOR activity was consistently observed in TAM across tumour models, and it was predominantly independent of intratumour location." (PMID 32567735, 2020). "Of note, the tumor revealed a strong immunohistochemical expression of not only mTOR but also its two main target proteins of the mTOR complex 1 by use of phosphorylation-specific antibodies against the active forms of the proteins, i.e., p‐4EBP1 and p‐RPS6." (PMID 31309284, 2020).
tumor (continued). "Molecular adaptations to tumor burden in skeletal muscles result in refractoriness to the anabolic signaling pathways (i.e., AKT, mammalian target of rapamycin (mTOR), JunB) usually activated by nutrition and growth-stimulating exercise (anaerobic physical activity)." (PMID 33255345, 2020). "To confirm that mTOR inhibitors can regulate the level of UBE2C, we extracted proteins from subcutaneous tumor tissues and showed that CCI779 could reduce the level of UBE2C and affect phosphorylated mTOR/AKT/PI3K." (PMID 33396624, 2020). "Moreover, here we also attempted to unravel the mechanism by which miR-135b activate the AKT/mTOR pathway to regulate the stem cells by inhibiting JADE-1 expression, which subsequently affects the stemness of PCSCs and promotes tumor growth." (PMID 32351328, 2020). "Once overloaded, mitochondrial reactive oxygen species (ROS) inhibits mTOR activity and OXPHOS performance to prevent mitochondrial dysfunction-induced tumor cell death, by disrupting MET dimerization to block its autophosphorylation and interaction with vacuolar ATP synthase (V-ATPase)." (PMID 33377662, 2020). "Recent findings also demonstrate that modulations in T cell anti-tumor immunity contribute to mTOR inhibitor efficacy, and reactivation of anti-tumor immunity promotes sustained responses in several other nonimmune-based treatments, including chemotherapy." (PMID 33036247, 2020). "Reports from other authors have shown that lapatinib, a dual inhibitor of EGFR and HER2, combined with the mTOR inhibitor rapamycin induced significant in vitro growth inhibition of TNBC cell lines and synergistically reduced tumour growth in TNBC cell-derived xenograft models." (PMID 32286420, 2020). "Furthermore, emerging evidence has highlighted the important role played by the kinase mammalian target of rapamycin (mTOR), the unfolded protein response (UPR) in the tumor biology controlled by oxygen deprivation and nuclear factor-κB (NF-κB)." (PMID 32751958, 2020). "In addition, well-studied tumor suppressors, such as PTEN (an Akt inhibitor), tuberous sclerosis 1 (TSC1), and TSC2 (mTOR inhibitors), give signals to stimulate autophagy, showing that raised autophagy signaling results in tumor suppression." (PMID 32121322, 2020). "Tumor outgrowths, induced by alterations in the AKT/mTOR pathway, lead to invasion." (PMID 32384682, 2020). "Consequently, SLC1A5 undergoes ubiquitination and degradation, leading to impaired glucose uptake, decreased mTOR activity and retarded TNBC tumor growth." (PMID 32296646, 2020). "In line with these evidences, the stimulation of mTOR cascade may enhance CXCL10-mediated T cells chemotaxis and anti-tumor immune responses in TME." (PMID 32483450, 2020). "Finally, in order to confirm the axis of miR-99b-mTOR and/or κB-ras2 and miR-99b-mTOR/IRF4 in vivo, we detected the expression of κB-ras2, mTOR and IRF4 in TAMs sorted from tumor-bearing mice after delivery of saline, miR-99b, V&Ctrl and V&miR-99b." (PMID 32948650, 2020). "Dihydroartemisinin (DHA), a semi-synthetic derivative of artemisinin known for its anti-tumor properties, was shown to induce ferritinophagy by regulating the activity of the AMP-activated protein kinase AMPK/mTOR/p70S6K pathway, thereupon triggering ferroptotic cell death." (PMID 33042852, 2020). "Meanwhile, western blot analysis of tumor tissues revealed that the expression levels of p-PI3K, p-AKT, and p-mTOR were decreased in CPT-treated mice compared with that of the control group, whereas the expression of PI3K, AKT, and mTOR was not significantly changed." (PMID 32903546, 2020). "Thus, CCT020312 inhibited tumor growth via the activation of the PERK/eIF2α/ATF4/CHOP signaling pathway and inactivation of the AKT/mTOR signaling pathway." (PMID 32508655, 2020).
tumor (continued). "Furthermore, activation of IGF-1R and mTOR and expression of EWS-FLI1 were strongly correlated with high BMI-1 levels, which is overexpressed in 80% of ES patients and induces tumor growth in a xenograft model." (PMID 32754598, 2020). "Second, we in silico compared the binding modes of the top 20 computationally-predicted oleacein mimetics to the two molecular targets originally involved in the capacity of oleacein to specifically suppress the functional traits of tumor-initiating CSC (i.e., mTOR and DNMT)." (PMID 33168787, 2020). "Although the high frequency of PI3K/AKT/mTOR pathway mutations in CRC and the results from a phase I study promised a robust anti-tumor activity, RAD001 failed to prevent disease progression in a phase II clinical trial." (PMID 32962206, 2020). "mTOR catalyzes the phosphorylation of multiple targets such as AKT, protein kinase C (PKC), and others, thereby regulating various biological processes such as tumor growth and metastasis." (PMID 32070055, 2020). "Elevated glutaminase and glutamate levels following mTOR (mammalian target of rapamycin) kinase inhibitor treatment promoted GBM survival while combined inhibition of mTOR kinase and glutaminase resulted in massive synergistic tumor cell death and growth inhibition." (PMID 32708312, 2020). "Immunohistochemical analysis of tumor sections showed overall higher 4E-BP1T37/46 and AKTS473 phosphorylation in untreated H460res compared with H460par tumors, indicative of elevated basal mTOR signaling in CDDP-resistant tumors in vivo." (PMID 32943635, 2020). "The outcomes of these trials remain to be determined, but studies in other tumor types have shown that PI3K/mTOR signaling inhibitors often lead to tumor stasis rather than shrinkage." (PMID 31324855, 2019). "This was associated with the increased expression of the E2F1 protein only in tumor tissue specimens obtained from those patients harboring three copies of E2F1, whilst surrounding non tumor-tissue showed both lower E2F1 protein expression and downstream-mTOR phosphorylation." (PMID 31338064, 2019). "Because the combination of eribulin with everolimus enhances anti-tumor activity, we next asked whether a combination of eribulin and other PI3K/AKT/mTOR inhibitors could achieve a similar result." (PMID 31480338, 2019). "At the same time, inhibitors of the PI3K/mTOR pathway investigated in preclinical studies as well as in clinical trials in GBM and other tumor types, show improved median survival, reduced local and metastatic growth, and tumor growth inhibition." (PMID 31324855, 2019). "WB of the tumor tissue lysates demonstrated that RA treatment induced apoptosis, inhibited the expression levels of the proliferation marker Ki-67, angiogenesis marker CD-31, and AKT/mTOR pathway proteins." (PMID 31293977, 2019). "Furthermore, downregulation of the Notch1 pathway by shRNA and MK0752 significantly inhibited the PI3K/AKT/mTOR signaling pathway via the decreased expression of CXCR4 in GICs, and weakened the self-renewal, invasion and tumor growth ability of GICs." (PMID 31382985, 2019). "The activity of mTOR was not upregulated, although basal levels of the mTOR substrate (eIF4E-BP) were significantly higher in tumor cells." (PMID 31354733, 2019). "Here, we hypothesized that both PI3K/mTOR and MEK/ERK pathways may function via regulating tumor microenvironment during CCA development." (PMID 30741922, 2019). "mTOR is a key kinase of PI3K/AKT downstream, it could regulate tumor cell proliferation, growth, survival and angiogenesis." (PMID 31007610, 2019). "Interestingly, miR-140 functions as a tumor-suppressive role in osteosarcoma tumor, which might be correlated with increased CTLs and reduced myeloid-derived suppressive cells and Treg cells through inhibiting mTOR signal pathway with significant synergistic anti-tumor effect." (PMID 31057561, 2019). "miR-7 is a tumor suppressor targeting PIK3CD, Akt, and mTOR." (PMID 30881383, 2019).
tumor (continued). "PARK2 exerts a tumor suppressive function in vitro and in vivo, including retarding growth, migration, invasion, and metastasis and promotes apoptosis of NSCLC cells through inhibition of the EGFR/AKT/mTOR pathway." (PMID 31508359, 2019). "Furthermore, we evaluated GSTO1-1 and GSTO2-2 expression in ccRCC and adjacent non-tumor tissue, as well as phosphorylation status of two important survival pathways, PI3K/Akt/mTOR and Raf/MEK/ERK." (PMID 31861116, 2019). "The median SIRT-3, p-mTOR and nuclear HIF-1α expression levels (percent of immunopositive tumor cells) were 35 (IQR 10–60), 0 (IQR 0–0) and 1 (IQR 0–10) in early-stage patients vs. 60 (IQR 10–90), 0 (IQR 0–0) and 0 (IQR 0–7.5) in advanced-stage patients, respectively." (PMID 30917505, 2019). "PD-L1 expression in tumor cells could be triggered by intrinsic cellular signaling molecules, including NF-κB, MAPK, PI3K, mTOR and JAK/STAT." (PMID 30925913, 2019). "This network demonstrates that 61 exosomal molecules may affect tumor progression through pathways controlled by key components including MET, Ras, RAF1, Mek, ERK1/2, MITF, BCL2, PI3K, Akt, mTOR, PD-1, KIT, JAK STAT3, or ETS1." (PMID 31681332, 2019). "Moreover, interaction of GSTO1 with activated downstream effectors of PI3K/Akt/mTOR and Raf/MEK/ERK pathway was shown in ccRCC tumor tissue." (PMID 31861116, 2019). "Many of the signal transduction pathways that regulate the tumor microenvironment, including Ras/Raf/MAPK, Raf/JNK, Rho/Rac/PAK, and PI3K/Akt/mTOR, are convergent downstream signaling pathways of RTKs, implicating their role in GBM invasiveness and aggressiveness." (PMID 31467533, 2019). "The expression levels of p-AKT1, p-mTOR, PFK and LC3 were observed in PDX tumours." (PMID 30717751, 2019). "The novelty of our study resides in the demonstration that the PI3K/mTOR inhibitor NVP-BEZ235 induces autophagy by AMPK/ULK1 pathway and the combinational treatment of NVP-BEZ235 and CQ further promote apoptosis to suppress tumor growth." (PMID 31871431, 2019). "LKB1 is known to inhibit the mTOR pathway through activation of AMPK, which may inhibit tumor cell proliferation, inhibit tumor cell polarization, and inhibit tumor metastasis." (PMID 31798532, 2019). "Both the PI3K/AKT/mTOR and the Wnt/β-catenin signaling cascades are known to be important canonical signaling pathways involved in tumor development and progression; approximately 50% of HCC cases display aberrantly activated PI3K/AKT/mTOR and Wnt/β-catenin signaling." (PMID 30678274, 2019). "On the contrary, the tumor feedback mechanisms to some well-recognized tumor drugs, such as, phosphatidylinositol-3-kinase (PI3K) and the mammalian target of rapamycin (mTOR)—the PI3K/mTOR signaling inhibitors, and resistance to anti-mitotic agent currently became the critical therapeutic issues." (PMID 31193204, 2019). "Activation of EGFR stimulates several downstream signaling cascades, including the RAS/ RAF/MAPK, PI3K/Akt/mTOR, JAK/Src/STAT, and phospholipase C gamma/protein kinase C pathways, triggering oncogene transcription and promoting tumor proliferation, survival, invasion, and drug-resistance." (PMID 31422383, 2019). "On the contrary, oe circ-FBXW7 down-regulated the mRNA and protein levels of NEK2 and mTOR, and enhanced PTEN expression in the two tumor models, which further confirmed that si circ-FBXW7 promoted CRC progression through upregulation of NEK2 and mTOR, and downregulation of PTEN." (PMID 31519156, 2019). "DEPTOR significantly promotes the growth of tumor cells in vivo and in vitro by inhibiting mTOR, which releases the negative feedback on the insulin PI3K/AKT pathway and therefore promotes cell survival and prevents apoptosis." (PMID 31228948, 2019). "Development of targeted therapies requires the identification of biomarkers to predict tumor sensitivity, and there is currently no consensus on the biomarker(s) predicting responses to mTOR inhibitors alone or in combination." (PMID 31627299, 2019).
tumor (continued). "Western blotting analysis from representative tumour tissues demonstrated that deoxyshikonin decreased PI3K, p-PI3K, Akt, p-Akt308 and mTOR proteins expression, which were consistent with the in vitro results (*p < 0.05, **p < 0.001, ***p < 0.0001 versus control (0 μg/mL))." (PMID 31230505, 2019). "Taken together, these results indicated that XL765 inhibited PI3K/mTOR signaling in vivo and pointed to a cytostatic effect of XL765 on tumor proliferation, consistent with previous studies indicating that PI3K/mTOR inhibition leads to tumor stasis." (PMID 31324855, 2019). "Application of mTOR inhibitors in UBC treatments should depend on careful selection of the tumor type: NMIUBC seems to respond to combination of rapalogs and other drugs, while only those MIUBC patients with phosphorylated mTOR are suitable to accept mTOR inhibitors treatments." (PMID 30754640, 2019). "A previous study found that Ad-TERTp-E1A-1504 has no harmful effects on normal cells but inhibits and kills TERT- and EphA3-positive tumor cells, which is mediated through the protein kinase B/mammalian target of rapamycin (AKT/mTOR) signaling pathway via autophagy induction." (PMID 31262977, 2019). "Moreover, mTOR inhibition downregulates both mRNA, protein levels, and the activity of the matrix metalloproteinases, MMP-9 and MMP-2, which promote tumor invasion through extracellular matrix degradation." (PMID 31387280, 2019). "Additionally, the AKT/mTOR axis is also reported to exert a positive role in EMT, promoting tumour metastasis." (PMID 30717751, 2019). "This drug-induced relief of the mTORC1-to-IRS1 negative feedback largely explained the modest anti-tumour activity by rapamycin and mTOR inhibitor analogues seen in the clinic." (PMID 35582276, 2019). "The expression of p-mTOR was not influenced by the diameter of the largest nodule (tumoral p = 0.9; peritumoral p = 0.37), neither by the total tumour diameter (tumoral p = 0.8; peritumoral p = 0.38)." (PMID 30650598, 2019). "Downregulation of the Pi3k/Akt/mTOR pathway by the Pi3k inhibitor Apitolisib or the Ras/Raf/MEK/ERK pathway by the MEK inhibitor Refametinib did not enhance the anti-tumor effect Tivantinib had on the viability of CC cells." (PMID 30850583, 2019). "In addition, other studies have identified several protective cellular pathways supporting the survival of tumor cells growing in glucose deprivation, including the unfolded protein response (UPR) pathway, the mTOR pathway, and the NF-ĸB pathway." (PMID 30704052, 2019). "There is a controversy whether these proteins act as oncogenes or suppressor genes in tumors, although there are literature data about a tumor-suppressive function of SIRT-3 and an oncogenic role of HIF-1α and p-mTOR in HCC." (PMID 30917505, 2019). "Although, these high levels of Akt did not lead to activation of mTOR via in muscle of these tumour-bearing hosts, which clearly showed that the mTOR pathway was compromised likely starting by the 14th day of tumour development." (PMID 30975087, 2019). "Co-IP assays and mass spectrometric analyses indicated that TRIM44 overexpression induces cell EMT through activating AKT/mTOR pathway via directly binding and stabilizing TOLL-like receptor 4 (TLR4), and TLR4 interference impeded TRIM44 induced tumor progression." (PMID 30922374, 2019). "Moreover, mechanistic target of rapamycin (mTOR), serine/threonine kinase activated by PI3K/AKT pathway, regulates tumor cell growth, survival, and metabolism via initiating downstream signaling network." (PMID 31905887, 2019). "Indeed, the mTOR signaling pathway not only increases HIF-1α synthesis, but also promotes tumor angiogenesis in CRC cells." (PMID 31430901, 2019). "We suggest that a clinically tolerable PI3K/mTOR inhibitor might be beneficial in LAM, as monotherapy or in combination with rapamycin, and in other mTORC1-driven neoplastic diseases." (PMID 31878201, 2019).